RN7SL628P (RNA, 7SL, cytoplasmic 628, pseudogene)
Gene: Miscellaneous RNA gene on chromosome 15 (30,612,724 to 30,612,960, forward strand). Ensembl gene ENSG00000277467.
Homologues: Orthologues: pig Metazoa_SRP (59% identical). Paralogues in human: RN7SL82P (100% identical), RN7SL469P (99% identical), RN7SL673P (99% identical), RN7SL719P (99% identical), RN7SL495P (99% identical), RN7SL196P (98% identical), RN7SL286P (98% identical), RN7SL539P (98% identical), RN7SL185P (97% identical), RN7SL796P (97% identical), Metazoa_SRP (92% identical), RN7SL106P (92% identical), and 707 more.